RAC1 (Rac family small GTPase 1)
Diseases named in the same sentence as RAC1 in open-access papers (continued):
Sharing a sentence is not in itself a finding about the gene and the disease.
gastric cancer (continued). "In this study, we found that HGF modulates Rac-1-regulated ROS production, ROS induces the expression of uPA via the MAPK pathway, and stimulates the invasiveness of human gastric cancer cells." (PMID 19497102, 2009). "sFRP1 reinstates glycogen synthase kinase 3β (GSK3β) activity, thereby facilitating Rac1 activation, while ectopic overexpression of Rac1 concurrently suppresses SMAD family member 3 (Smad3) activity; these interactions collectively enhance the malignant phenotype of EMT in gastric cancer." (PMID 41188920, 2025). "Rho GDP dissociation inhibitor 2 (RhoGDI2) recruits Rac1 to Filamin A (a sizeable cytoskeletal protein), resulting in enhanced interaction between Rac1 and Rho GEF Trio to increase Rac1 activity and promote gastric cancer cell invasion." (PMID 41188920, 2025). "Our previous studies revealed that RAC1 can increase the sensitivity of gastric cancer to chemotherapy, but the specific mechanism is not yet understood." (PMID 39224538, 2024). "The RNA interference vectors of Rac1 and Prex1 genes were constructed to investigate the impact of silencing Rac1 and Prex1 expression on EMT, apoptosis, and cell viability of TGF-β1-treated gastric cancer cells." (PMID 37434402, 2023). "Next, we investigated whether RhoGDI2 could enhance the interaction between Rac1 and FLNA in gastric cancer cells." (PMID 35008419, 2022). "Rac1 and CDC42 expression were detected by IHC with the TMA of gastric cancer tissues." (PMID 31754397, 2019). "We next sought to determine whether Rac1 activation was needed in the cell migration and invasion of SNU-216 and NUGC-4 gastric cancer cells." (PMID 28099468, 2017). "We also found that Rac1 is positively regulated by RhoGDI2 in gastric cancer cells (data not shown) and activated Rac1 mediates NF-κB activation, which induces Snail upregulation in RhoGDI2-overexpressing gastric cancer cells." (PMID 24721928, 2014). "Alternatively, ongoing studies in our laboratory have revealed that Rac1, but not RhoA or Cdc42, is activated in RhoGDI2-overexpressing gastric cancer cells." (PMID 24185104, 2013). "As Cdc42 GTPase inhibitors are a selective, reversible, non-competitive inhibitor of Cdc42 GTPases, these results indicate the possible involvement of Cdc42 in the Ln511-E8 fragment-induced enhanced adhesion of gastric cancer cells, whereas Rac1 and Rho are not or only partially involved." (PMID 35723363, 2022). "In the analysis of miRNA related to gastric cancer metastasis, it was found that the high level of miR-345 was positively correlated with the good prognosis of patients, because miR-345 down-regulated the transmission of epidermal growth factor receptor pathway substrate 8 (EPS8) and Rac1 signal." (PMID 34079763, 2021). "Furthermore, we observed that hypoxia stimulated Rac1 activation, which may serve as an important mediator for NEDD9/MICAL1-facilitated gastric cancer cell migration." (PMID 31019460, 2019). "Interestingly, the expression of Rac1 in gastric cancer tissues was higher than in the matched adjacent non-tumor tissues, its expression level was significantly associated with TNM stage." (PMID 23826132, 2013). "Simultaneously, experimental results showed that after inhibiting Rac1 activity, the role of ITGB6 in gastric cancer cell activity, migration, and invasion disappeared, suggesting that ITGB6 might play a role in the proliferation, migration, and invasion of gastric cancer cells through Rac1." (PMID 38344200, 2024). "Similar to others findings, here we found that hypoxia elevated both Rac1-GTP and Cdc42-GTP levels, but not RhoA-GTP in gastric cancer cells." (PMID 31019460, 2019). "Furthermore, we found that NKX6.3 functions as a negative transcriptional regulator of RhoA, Cdc42, Rac1, Rac2, Skp2 and c-Myc genes and completely inhibits c-Myc-p300/CBP-Skp2-Miz1 and Max complex formation, thereby preventing gastric cancer cell migration and invasion." (PMID 27333045, 2016).
ovarian carcinoma (68 papers, 2010 to 2025). A malignant neoplasm originating from the surface ovarian epithelium. "RAS‐associated C3 botulinum toxin substrate 1 (RAC1) is overexpressed in ovarian cancer patients and is negatively associated with patient outcomes." (PMID 39224538, 2024). "EMT in ovarian cancer cells is dependent on RAC1 activation through the SOS1/EPS8/ABI1 complex, associated with increased MEK-ERK and SRC activation." (PMID 39354505, 2024). "Despite evidence that elevated expression or activity of Rac1 is associated with worse prognosis in ovarian cancer, there is limited knowledge on the impact of Rac1 or Cdc42 inhibition in vivo." (PMID 33413202, 2021). "Rac1 overexpression in ovarian cancer is associated with early tumor recurrence and decreased patient survival." (PMID 33413202, 2021). "The results demonstrate that high total RAC1 mRNA expression is associated with worse outcomes and concur with a report that analyzed Rac1 as a risk factor in a cohort of 150 Chinese ovarian cancer patients." (PMID 30261690, 2018). "The prognostic or diagnostic significance of overexpression of canonical Rac1 in ovarian cancer and/or the potential role(s) of the hyperactivated, fast cycling Rac1b isoform remain open questions." (PMID 30261690, 2018). "Our own retrospective analyses demonstrate a benefit of racemic ketorolac in ovarian cancer patients and R-ketorolac inhibits Rac1 and Cdc42 GTPases and tumor associated behaviors of human ovarian tumor cells both in vivo and in vitro." (PMID 26558612, 2015). "PLD is implicated in cell spreading of ovarian cancer cells after PA was found to interact directly with Rac1 and to mediate the translocation of GTP-Rac1 to the plasma membrane." (PMID 23574936, 2013). "In ovarian cancer, increased activation of Rac1 was also associated with increased invasion." (PMID 40777010, 2025). "However, a splice variant of Vav3, a GEF and enhancer of Rac1 activity, is overexpressed in multi-drug resistant stem cell-like fractions of ovarian cancer cells." (PMID 30261690, 2018). "Those authors showed that the gel reduced the invasion of ovarian cancer cells in an immunocompromised mouse model, specifically through the inhibition of signals initiated by epidermal growth factor and the reduced expression of proteins linked to metastasis (such as Rac1 protein)." (PMID 39255313, 2024). "More recently, R-ketorolac became the first FDA-approved Rac1/Cdc42 inhibitor and has been shown to significantly reduce cancer spread in ovarian cancer." (PMID 41188920, 2025). "Inhibitors targeting RAC1 (EHop-016) and MEK (PD98059) have shown efficacy in suppressing malignant tendencies in ovarian cancer cells that overexpress TEM8 in vitro via the Rac1/Cdc42/JNK and MEK/ERK/STAT3 pathways." (PMID 37998358, 2023). "In ovarian cancer cells, the activin A migratory effect was dependent on Akt, Erk and Rac1 activation." (PMID 36717814, 2023). "In vitro: Fascin-1 silencing or pharmacological inhibition decreased cancer cell migration and impaired Cdc42 and Rac1 activityIn vivo: reduced ovarian cancer metastasis formation in mice." (PMID 37511011, 2023). "Earlier studies have also demonstrated effect of Ketorolac in ovarian cancer through inhibition of Rac-1 and Cdc4215." (PMID 37024613, 2023). "Recent studies have identified that racemic ketorolac (R-Ketorolac) is a robust Rac1 inhibitor that inhibits ovarian cancer metastasis." (PMID 37866630, 2023). "The Food and Drug Administration (FDA)-approved analgesic drug R-ketorolac (Toradol) inhibits Cdc42 and Rac1 in ovarian cancer cells and is currently in clinical trials (NCT02470299)." (PMID 36355541, 2022). "Ketorolac has a novel pharmacologic activity by inhibiting Rac1 and Cdc42, potentially contributes to the survival benefit in women with ovarian cancer and reduces ovarian cancer-specific mortality." (PMID 35154449, 2022).
ovarian carcinoma (continued). "In ovarian cancer, we reported elevated Rac1 and Cdc42 protein levels in high grade vs. low grade tumors and elevated mRNA expression of a constitutively active splice variant Rac1b in low grade ovarian tumors." (PMID 33413202, 2021). "R- ketorolac, as a component of a racemic drug approved by the FDA to relieve pain, is a dual Rac1/Cdc42 inhibitor, which can reduce the invasive biological behavior of ovarian cancer and glioblastoma." (PMID 34079763, 2021). "The human equivalent dose of R-ketorolac partially inhibited Rac1 and Cdc42 and the magnitudes of inhibition were similar to those measured in samples from ovarian cancer patients who received the racemic drug." (PMID 33413202, 2021). "Taken together, these studies support potential benefits of inhibiting Rac1 and/or Cdc42 in ovarian cancer." (PMID 33413202, 2021). "Inhibition of Rac1 and Cdc42 in ovarian cancer patients can be achieved by the administration of racemic ketorolac, a mix of the R- and S-enantiomers." (PMID 32443784, 2020). "A published study showed that R-enantiomer of the anti-inflammatory drug ketorolac inhibited Rac1 and Cdc42 and showed a better outcome in ovarian cancer treatment." (PMID 32443784, 2020). "Inhibition of the Erk1/2 upstream regulator MEK1/2 constitutively abolishes active Rac1-induced EMT in ovarian cancer cells." (PMID 32585958, 2020). "To clarify the carcinogenic effect of ESRP1 in ovarian cancer, we found that ESRP1 inhibited cancer cell migration and invasion by alternatively splicing cytoskeleton-associated proteins Rac1 and EPB41L5, and promoted colonization and colony formation." (PMID 32467669, 2020). "R-naproxen demonstrated the same activities against Rho-family GTPases Rac1 and Cdc42 as R-ketorolac in immortalized ovarian cancer (OvCa429, OvCa433) and cervical cancer (HeLa T4+) cells." (PMID 32443784, 2020). "The current status of the literature indicates that both classes of targets (COXs and Rac1/Cdc42 GTPases) are important in ovarian cancer progression, metastasis, and patient outcome." (PMID 31344967, 2019). "In ovarian cancer cell lines, knock down of Rac1 expression reversed epithelial to mesenchymal transition (EMT), inhibited tumor cell migration and invasion, and reduced tumor growth in a xenograft model." (PMID 31344967, 2019). "This prediction was supported by the finding of time-dependent inhibition of Rac1 and Cdc42 activity in cells retrieved from the peritoneal compartment of these post-surgical ovarian cancer patients after ketorolac administration." (PMID 31344967, 2019). "The rs927062 variant of ARHGAP5 was found to be associated with increased endometrioid and invasive serious ovarian cancer risk and a statistically significant decrease of ARHGAP5 protein which would be predicted to increase Rac1 and RhoA activity." (PMID 31344967, 2019). "As for ovarian cancer chemotaxis, RhoA and Rac1 were suggested to play independent roles in the chemotactic migration of ovarian cancer cells, inhibition of RhoA and Rac1 decreased cancer cell migration in LPA-induced chemotaxis." (PMID 30795761, 2019). "Clinical trials using R-ketorolac alone would offer an opportunity to directly test the predicted benefit of a Rac1/Cdc42-selective inhibitor in ovarian cancer patients." (PMID 31344967, 2019). "In fact, blocking or silencing of CXCR4 was found to significantly reduce RhoA and Rac-1/Cdc42 expression levels and decrease ovarian cancer cell migration." (PMID 30261690, 2018). "Similar to our findings, recent work has also demonstrated the utility of combining SRC and MEK inhibitors in the ovarian cancer setting, where the combination of selumetinib and saracatinib abolished Rac-1 mediated EMT of ovarian cancer cells." (PMID 29435137, 2018). "A more complete understanding of the complexities of Rac1 regulation by the ovarian cancer TME will require further study." (PMID 30261690, 2018).
ovarian carcinoma (continued). "For example, an shRNA essentiality screen of 29 ovarian cancer cell lines showed SKOV3, COV362, JHM + OM1 and SNU840 to have significantly decreased growth fitness with the loss of Rac1 (Harmonizome Achilles." (PMID 30261690, 2018). "Ligands for RTKs such as the EGF receptor and VEGF receptor are prevalent in ovarian cancer ascites and regulate Rac1 activation through multiple mechanisms." (PMID 30261690, 2018). "In this review we discuss evidence for Rac1 activation within the ovarian tumor microenvironment, mechanisms of Rac1 dysregulation as they apply to ovarian cancer, and the potential benefits of targeting aberrant Rac1 activity in this disease." (PMID 30261690, 2018). "The potential for Rac1 contribution to extraperitoneal dissemination of ovarian cancer is addressed." (PMID 30261690, 2018). "Rac1 is at the nexus of numerous signaling pathways stimulated by the ovarian cancer TME and has broad roles in cancer beyond the well-recognized regulation of actin remodeling, tumor cell adhesion and migration." (PMID 30261690, 2018). "The combined data indicate that further study of Rac1 activation in ovarian cancer by tyrosine kinase receptors and their interfaces with G-protein coupled receptors is warranted." (PMID 30261690, 2018). "Addressing the function of Rac1 hyperactivation in ovarian cancer is an important research area because of the known roles of Rac1 in cancer metastasis and recurrence." (PMID 30261690, 2018). "Although the relationship between Rac1 expression and/or elevated activity and cancer stem cells has been reported for several cancer types, there is little information for ovarian cancer." (PMID 30261690, 2018). "The concentration of R-ketorolac was sufficient to inhibit Rac1 activity in cells retrieved from the peritoneal compartment of these post-surgical ovarian cancer patients." (PMID 30261690, 2018). "Insight into possible mechanisms leading to Rac1 overexpression and hyperactivation in ovarian cancer is garnered from analyses of the Catalogue of Somatic Mutations in Cancer (COSMIC) and The Cancer Genome Atlas (TCGA) databases as detailed below." (PMID 30261690, 2018). "We reported that Rac1 protein is overexpressed and hyperactivated in ovarian cancer patient samples." (PMID 30261690, 2018). "Ovarian cancer cells secrete TGFβ1 to activate a TGFβ1/RAC1/SMAD-mediated signaling pathway in mesothelial cells that results in secretion of fibronectin by mesothelial cells and increased ovarian cancer cell adhesion, invasion, and proliferation." (PMID 28275576, 2017). "Given that Rac1 and Cdc42 are highly expressed and active in ovarian cancer, inhibitors of these 2 GTPases have been tested in immortalized and primary human ovarian cancer cells." (PMID 27104658, 2016). "The R enantiomer of ketorolac, (ketorolac is given as an anti-inflammatory drug), can inhibit Rac1 and Cdc42 and was shown to improve patient outcomes in treatment for ovarian cancer." (PMID 27104658, 2016). "RAC1 and other members of the Rho family of GTPases have been implicated as key modulators of sensitivity to DNA-damaging agents; in particular, chemical inhibition of RAC1 has been shown to sensitize drug-resistant ovarian cancer cell lines to cisplatin." (PMID 26052356, 2015). "In summary, our results conclusively establish for the first time that Hax-1 is critically required for the Rac1-cortactin interaction and subsequent invasive migration of ovarian cancer cells." (PMID 25053987, 2014). "A similar small reduction in Rac activation has been observed upon CrkI/II knockdown in MCAS ovarian cancer cells, further supporting the idea that Crk represents only one of several pathways that can activate Rac1." (PMID 22569336, 2012). "RAC1 inhibition repressed EMT in mesenchymal-like ovarian cancer cells." (PMID 39700131, 2024).
ovarian carcinoma (continued). "In breast and ovarian cancers, physical interactions of CD44v3 with the extracellular matrix component hyaluronic acid and the cytoskeletal protein Ankyrin induce tumour cell migration through the stimulation of Rac1 and RhoA Rho GTPases." (PMID 36528833, 2023). "Taken together, these findings suggest that Rac1 may be a viable target for further drug development to attenuate aggressive tumor behaviors in ovarian cancer." (PMID 33413202, 2021). "Besides, the increased expression of Rac1 has been observed in many types of cancer, such as gastric, oesophageal, gallbladder, lung, hepatocellular, breast and ovarian cancer." (PMID 32731493, 2020). "These authors performed a series of very elegant in vitro and in vivo experiments, showing that TGF-β produced by ovarian cancer cells can activate a TGF-β receptor/RAC1/SMAD-dependent signaling pathway in the mesothelial cells, what induces EMT and results in overexpression of fibronectin." (PMID 31936272, 2020). "Additionally, elevated expression and activity of Rac1 and Cdc42 was detected in tissues of ovarian cancer patients." (PMID 32443784, 2020). "Rac1 is considered as a potential target for anticancer therapy in ovarian cancer." (PMID 32443784, 2020). "Furthermore, alterations in the expression level of Rac1 were found in a cohort of 150 specimens obtained from women with epithelial ovarian cancer." (PMID 32443784, 2020). "R-ketorolac inhibitor was identified in a study on immortalized human ovarian adenocarcinoma cells (SKOV-3ip) and primary patient-derived ovarian cancer cells with similar effects to those of small molecule inhibitors of Rac1 (NSC23766) and Cdc42 (CID2950007/ML141)." (PMID 32443784, 2020). "However, a specific inhibitor of another GTPase, Rac1, is under development for ovarian cancer treatment and seems promising in cases where the Rac1 is abnormal." (PMID 31448273, 2019). "Here, we briefly highlight how some of these interactions may promote ovarian cancer metastasis through Rac1-dependent mechanisms." (PMID 30261690, 2018). "The overall findings suggest that ovarian cancer patients may benefit from inhibition of Rac1 in the clinical setting." (PMID 30261690, 2018). "Although more research is needed regarding specific contributions of aberrant Rac1 activity in ovarian cancer and disease dissemination with respect to specialized microenvironments, current knowledge suggests benefits of targeting Rac1, alone or in combination, for disease treatment." (PMID 30261690, 2018). "The composite data are suggestive that Rac1 hyperactivation is an important driver in ovarian cancer and may result largely from the misregulation of GEF and GAP regulatory cascades rather than through activating mutations in Rac1 itself." (PMID 30261690, 2018). "Since RhoA and Rac1 are often reciprocally active, connections between the two GTPases may need further analysis in ovarian cancer." (PMID 30261690, 2018). "R-ketorolac inhibited Rac1-dependent cellular functions in ovarian cancer cell lines and primary cells including inhibition of growth factor-stimulated formation of filopodia, cell adhesion to fibronectin and type I collagen, development of invadopodia and tumor cell migration." (PMID 30261690, 2018). "In ovarian cancer cell lines, knock down of Rac1 expression decreased fibronectin production, reversed EMT as measured by increased E-cadherin and decreased vimentin expression, inhibited tumor cell migration and invasion and reduced tumor growth in a xenograft model." (PMID 30261690, 2018). "Thus our results presented here describe for the first time that Hax-1 interaction is required for the association between Rac1 and cortactin and that these multiple interactions are required for the LPA-stimulated migration of SKOV3 ovarian cancer cells." (PMID 25053987, 2014).